APC (APC regulator of Wnt signaling pathway)
Diseases named in the same sentence as APC in open-access papers (continued):
Sharing a sentence is not in itself a finding about the gene and the disease.
cancer (continued). "In addition, crosstalk with other cancer-related signaling pathways, such as KRAS, APC, and LKB1 mutations, have all been reported to contribute to upregulate the YAP/TAZ activity in cancers." (PMID 30805310, 2019). "In the cited study, even if the WNT pathway was notably activated in dysplastic serrated lesions and BRAF mutant cancers, it was not due to truncating APC mutations, suggesting the existence of alternative mechanisms of activation of the WNT signaling." (PMID 31330830, 2019). "Our meta-analysis showed statistical significance between HBV-positive carcinoma serums and HBV-negative carcinoma serums for the methylation of two genes, including p16 (the overall OR = 2.51, 95% CI = 1.16-5.44, p = 0.02) and APC (the overall OR = 5.11, 95% CI = 2.09-12.52, p = 0.0004)." (PMID 31772678, 2019). "Conversely, Mcl‐1 would be stabilised and apoptosis inhibited by a strategy targeting the APC/C directly, which might have less desirable consequences for cancer chemotherapy." (PMID 29987118, 2018). "More moderate missense APC mutations occur in BRAF mutant/MSI cancers which may influence the Wnt signal, and it was found that 87% of BRAF mutant/MSI cancers mutate RNF43 which is a negative regulator of the Wnt signal." (PMID 30598662, 2018). "APC is a cancer-related protein; thus, PPI candidates with APC are likely to be related to cancer." (PMID 29745830, 2018). "Moreover, recent studies revealed interaction of APC and KRAS mutations in the various stages of colorectal tumorigenesis and even in metastasis accompanying activation of the cancer stem cells (CSCs)." (PMID 29872723, 2018). "Hence, hyperactive transcription of Wnt signaling and downregulation of Wnt signaling related tumor suppressor genes such as APC, indicate higher levels of self-renewal and dyregulated proliferation of these cancer cells." (PMID 29433490, 2018). "Both, APC and RNF43, are frequently mutated negative regulators of the Wnt/β‐catenin signaling pathway —a pathway that is aberrantly regulated in various cancers." (PMID 29467179, 2018). "The fact that we were not able to obtain complete USP7 KO in APC-mutated CRC cells indicates the essential role of USP7 in cancer cell survival." (PMID 29045831, 2017). "Despite extensive research on Wnt signaling and CRC over the past 20 years, clinically approved drugs targeting Wnt signaling in APC mutation cancer do not exist." (PMID 29045831, 2017). "Unlike β-catenin and adenomatous polyposis coli (APC), both of which are frequently mutated in cancer, oncogenic mutations have not been observed in LRP6." (PMID 28966723, 2017). "In addition, PIK3CA.E542K, PTPN11.G268S, AKT1E17K and APC.T1556Nfs*3 were also observed in multiple cancer types." (PMID 29038591, 2017). "Such mutations are not universal in all cancer types and while APC mutations occur more frequently in cancers of the colon, the lung is rarely affected by such mutations." (PMID 28870231, 2017). "APC alterations typically occur at early steps of the colorectal adenoma–carcinoma sequence, a typical feature of “trunk” genetic events, present in all cancer cells and therefore therapeutically attractive." (PMID 28100566, 2017).
cancer (continued). "The Wnt/β-catenin pathway and associated proteins such as glycogen synthase kinase-3β (GSK-3β) and adenomatous polyposis coli (APC) are among the most frequently altered cellular molecules and they are influenced by many of the dietary compounds showing anti-cancer activity." (PMID 28238104, 2017). "The genetic changes involve the initial loss or mutation of APC/β-catenin genes for the formation of aberrant crypts foci, mutations of KRAS/BRAF to advanced adenoma, and other acquired mutations for transformation to carcinoma." (PMID 29069792, 2017). "Furthermore, inactivation of Fzr has been shown to result in replicative stress, cell cycle arrest and cell death, suggesting that APC/CFzr as well as APC/CCdc20 are valid targets for anti-cancer therapy." (PMID 27655696, 2016). "Notably, a combination of GSTP1, RARß2, RASSF1a, and APC has been the best at discriminating cancer from non-cancer specimens." (PMID 27835705, 2016). "Moreover, pro-TAME with cell permeable activity disrupted the APC-Cdc20/Cdh1 interaction to reduce APC activation, leading to cell death in multiple cancer cell lines." (PMID 27626499, 2016). "For example, the gene CTNNB1 has more than 1.5-fold higher expression in the APC mutant cell lines than in the APC wide-type cell lines, raising the possibility that the viability of APC mutant cancer cells might depend on CTNNB1's expression." (PMID 26937901, 2016). "APC mutation has been found in over 80 % of CRC cases and significantly less frequently in sporadic high microsatellite instability cancers than in low microsatellite instability or microsatellite instability cancers." (PMID 27595705, 2016). "Next, the clinical significance of APC promoter hypermethylation was first determined in cancer." (PMID 27670526, 2016). "Despite the exciting new findings for APC/C, following future efforts could further enhance our understanding of APC/C and promote its translational value in anti-cancer treatment." (PMID 27418942, 2016). "Another gene TDO2 has significant lower GPVs in the APC mutant cell lines than in wide-type cell lines (P value <10–4), and significantly higher level of expression in APC mutant cancer cell lines than in wide-type cell lines (P value = 0.021, fold-change = 3.02)." (PMID 26937901, 2016). "Multiple research groups have demonstrated that constitutive activation of the canonical Wnt pathway in cancer cells is due to loss-of-function or deletion mutations in key negative factors in Wnt/β-catenin signaling, such as APC, Axin, or β-catenin." (PMID 26992223, 2016). "Our results suggest that this gene could be synthetic lethal to APC since it has lower GPVs, and is highly expressed in the APC mutant cancer cell lines." (PMID 26937901, 2016). "This study also offers two possibilities : First, to prevent reactivation of dormant cancer cells by inhibiting NHEJ DNA repair, and second, to enhance chemotherapy sensitivity by inhibiting APC/C activity and reducing chemotherapy-resistant dormant cancer cells." (PMID 27009858, 2016).
cancer (continued). "It has been reported that defects in the APC gene lead to inherited and sporadic forms of colon cancer and may account for up to 80% of the cancers in colon tissue." (PMID 26992223, 2016). "As proposed, knockdown of p21 or inhibition of APC/C by TAME could obviously increase cancer cells’ chemosensitivity to 5-FU, which is consistent with studies demonstrating that TAME could inhibit the mitotic block and increase paclitaxel efficacy." (PMID 27009858, 2016). "Thus, APC promoter methylation, which acts as a non-invasive biomarker, can be used to distinguish BC patients from cancer-free controls." (PMID 27478702, 2016). "As elevation of Cdk activity has been found in most cancer cells, Cdh1 might largely exist in an APC-free population in these cancer cells, which directly interacts with WWP2 to facilitate its auto-inhibition." (PMID 27462441, 2016). "Moreover, rs2707765 affects APC expression, and a lower APC expression correlated with more aggressive cancer and a worse clinical outcome." (PMID 27898031, 2016). "It is also worth noting that in cancer cells inhibition of APC/C by chemical inhibitor pro-TAME could sensitize Top2α inhibitors." (PMID 27418942, 2016). "By comparisons of doubling time and MDR between the mutant and wild-type NCI-60 cell lines, we revealed that mutations of APC, KRAS, and PIK3CA might correlate with enhanced malignancy of cancer cells." (PMID 26937901, 2016). "For example, APC loss of function, considered to be a very common early event in sporadic CRC, is much less frequent and usually occurs late in the colitis-associated dysplasia-carcinoma sequence." (PMID 27087592, 2016). "It has been suggested that inactivation of APC/CCdh1 might contribute to cancer growth, through stabilization of oncogenic substrates that fuel proliferation." (PMID 26423134, 2015). "The mutation in the APC gene does not trigger cancer but rather, it reduces the body’s ability to protect cells from becoming cancerous." (PMID 26436104, 2015). "However, the effectiveness of these treatments is impaired in APC-mutant cancers as a result of a functional BER capacity and should be considered when these drugs are administrated." (PMID 25301724, 2014). "Importantly, in APC-mutant cancer cells, the distribution of Axin1 and β-catenin complexes strongly resembles that of Wnt-stimulated cells." (PMID 25392450, 2014). "Thus, we show that the distribution of β-catenin complexes in APC-mutant cancer cells is highly similar to those of Wnt3a-stimulated cells." (PMID 25392450, 2014). "Finally, we show that the distribution of β-catenin complexes in APC-mutant cancer cells is strikingly similar to that of Wnt-stimulated cells, including the accumulation of phosphorylated β-catenin." (PMID 25392450, 2014). "Based on these findings, we postulate that both the phosphorylated and non-phosphorylated forms of β-catenin may contribute to target gene transcription in Wnt-stimulated cells and APC-mutant cancer cells." (PMID 25392450, 2014). "Indeed, APC promoter hyper-methylation has been found to occur in a variety of human cancers including breast (44%) and lung (53%) and other cancers." (PMID 24224156, 2013). "More important, no recommendations exist for the management of cancer patients with germline APC gene mutations, particularly concerning postoperative radiotherapy." (PMID 26425572, 2013). "There exist no recommendations for the management of cancer patients with germline APC gene mutations." (PMID 26425572, 2013).
cancer (continued). "In this sense, reduction in the protein synthesis rate in a cell is of great importance in respect of cancer therapy, and this is beautifully demonstrated in APC mutant mice in which inhibition of mTOR drastically suppressed intestinal polyp formation and reduced mortality." (PMID 23592547, 2013). "Studies comparing NTAT with benign prostate tissue and/or cancer tissue identified alterations in gene expression, telomere DNA content, mitochondrial DNA, and prevalence of methylation in some genes, including APC, GSTP1 and RARβ2." (PMID 23874531, 2013). "Specifically, we recurrently detected large deletions, small indels, and an overall significantly higher mutation rate in both adenomas and adenocarcinomas in APC coding exons, in comparison with 10 other genes known to be altered in human CRC or other human cancers." (PMID 23251390, 2012). "Furthermore, the adenomatosis polyposis coli (APC) protein was present in the ‘Regulation of actin cytoskeleton’, ‘Wnt signaling pathway’, ‘Colorectal cancer’, ‘Pathways in cancer’, and ‘Endometrial cancer’." (PMID 22514598, 2012). "Hypermethylation of APC implies silencing of this gatekeeper function, making the cell vulnerable to further epigenetic and genetic changes and, thus, progression toward invasive cancer." (PMID 22191037, 2011). "To determine whether Cdc42 could interact with more physiologically relevant versions of APC we carried out FRET experiments with full-length APC and a truncation mutant linked with cancer, APC1–1638." (PMID 21311754, 2011). "Degradasome assembly is also attenuated in APC mutant cancer cells." (PMID 22645652, 2011). "Our data also suggest that the targeted inhibition of the signaling pathways specifically hyper-activated downstream of APC mutation, such as Src and JNK, may prove to provide a therapeutic benefit for these cancers." (PMID 22216254, 2011). "These cancer cells are known to express wild type APC and β-catenin." (PMID 20711340, 2010). "APC mutation is less frequent in MSI-CRC than in CIN-CRC, while activating mutations in CTNNB1, though widespread throughout the spectrum of human cancer, are rare in MSI-CRC." (PMID 19956716, 2009). "Indeed, Waki and coworkers have observed frequent DNA methylation of APC in non-cancer lung and other organs." (PMID 17967182, 2007). "In addition, one of the major player genes involved in cancer development in the Wnt pathway, APC, was also reported to show methylation-dependent silencing of expression." (PMID 17968429, 2007). "Our observations might therefore predict that mutant APC should also localise to sites of cell-cell adhesion in cancer cells, as long as these cells were capable of assembling functional intercellular junctions." (PMID 16423286, 2006). "As in vitro expansion capacity is dependent upon both the number and stimulatory capacity of CDld antigen-presenting cells, reduced numbers of and/or functionally defective CDld APC may suppress NKT activation in cancer patients." (PMID 15520823, 2004). "Mutation patterns in the APC gene differed significantly between PG and NPG carcinomas." (PMID 15213719, 2004). "APC mutations were recently correlated with a poor response to immunotherapy in CRC, and given the role of both receptors in the cancer immune response, it is tempting to speculate that the upregulation of P2X7 and A2A in these patients could be partly responsible for this phenomenon." (PMID 40759630, 2025). "However, APC/CCdh1 is also active in G2 allowing DNA-repair prior to mitotic entry, whilst untimely APC/C activity may occur in cancer cells, where the SAC is often defective and the presence of supernumerary centrosomes may cause prolonged mitotic delay." (PMID 39789388, 2025). "Thus, the APC/C may be a potentially ”sensitized” target specifically within cancer cells suffering from an elevated load on the proteostasis machinery." (PMID 40650052, 2025).
cancer (continued). "Moreover, in adenomatous polyposis coli (APC), a key tumor suppressor gene, deficient CRC, tryptophan 2,3-dioxygenase 2 (TDO2) was identified as an essential effector that, via Kyn-AhR pathway, upregulate glycolysis and anabolic cancer cell growth." (PMID 40361394, 2025). "Indeed, it is widely accepted that CRC develops through an adenoma to carcinoma sequence in both FAP and sporadic CRCs and that mutations in the adenomatous polyposis coli (APC) gene are the key driver mutational events in the initiation and development of most (>85%) CRCs." (PMID 41514557, 2025). "However, despite decades of research, no approved drugs targeting WNT signaling in APC-mutated cancer exist." (PMID 36669491, 2023). "The APC:c.3902T>A variant was highly detected among Ashkenazi Jews and frequently detected among non-Ashkenazi Jews; however, there was mostly no clinical correlation or matching to the cancer type or cancer syndrome diagnosed." (PMID 38201524, 2023). "However, they did not consider the presence of cancer at the time of the first surgery and APC mutation." (PMID 35053462, 2022). "Furthermore, they can give rise to organoids in vitro (small and large intestine), and might serve as cancer-initiating cells upon injury and deletion of adenomatous polyposis coli (APC)." (PMID 35237268, 2022). "Cdc20 overexpression is accompanied by the overexpression of various other genes associated with APC/C impairment in diverse cancers, including overexpression of other APC/C substrates, indicating that impairment of the APC/C and not specifically Cdc20 overexpression is important for tumorigenesis." (PMID 35832196, 2022). "Similarly, APC can be detected in all cancer cells but with low RNA cell-type specificity." (PMID 35303016, 2022). "Thus, the increased compound efficacy may be related to the dual activity, in line with a recent study reporting that inhibition of APC/CCDC20 enhances the sensitivity of cancer cells to microtubule interfering agents." (PMID 35490245, 2022). "In addition, APC germline mutations were found in some patients who had not a second cancer and family history of cancer." (PMID 35372080, 2022). "Hence, abrogating the APC-Asef interaction paves the way for anti-cancer drug design." (PMID 33670371, 2021). "However, a definitive link between spindle orientation in stem cell divisions and gut homeostasis remains unclear, and thus, whether cytoskeletal APC dysfunction might drive the path to cancer." (PMID 33348689, 2020). "Given that loss of APC/CCdh1 activity is associated with genomic instability and tumorigenesis it is tempting to speculate that upregulation of Claspin, Chk1, Cyclin A, and Plk1 may contribute to genomic instability and cancer, in part, via antagonism of APC/CCdh1." (PMID 32345958, 2020). "Deregulation of Wnt signaling contributes to many cancers, resulting from both activating mutations of the proto-oncogene CTNNB1 (encoding β-catenin), and loss of function mutations in negative regulators of the pathway, such as APC (encoding Adenomatous Polyposis Coli)." (PMID 32210188, 2020). "In addition to the multiple findings of Wnt directly impacting stem cells and cancer stem cells (CSCs), we made the novel observation that the loss of APC results in an increase in stem cells, independent of Wnt activation." (PMID 33105836, 2020). "Thus, this evidence suggests that PTTG2 may interact with the APC and Aurora-related signaling pathways to regulate cancer progression." (PMID 33173433, 2020).